CBY3 (chibby family member 3)
Description:
Plays a key role in the correct positioning of the annulus, a septin-based ring structure in the sperm flagellum, serving both as a physical barrier and a membrane diffusion barrier that separates the midpiece (MP) from the principal piece (PP) (By similarity). This positioning is essential for proper sperm motility and function (By similarity). CBY3 interacts with CIBAR1 to form a complex which localizes to the curved membrane region of the flagellar pocket (By similarity). By doing so, may provide stability and rigidity to the periannular membrane to prevent membrane deformation (By similarity). This function is crucial for halting annulus migration at the proximal end of the fibrous sheath-containing PP (By similarity).
Tractability: PROTAC: ubiquitination databases record sites on it.
Gene: Protein-coding gene on chromosome 5 (179,678,560 to 179,681,034, reverse strand). Ensembl gene ENSG00000204659.
Subcellular location: Cell projection, cilium, flagellum
Subcellular location (Human Protein Atlas): Nucleoplasm
Gene Ontology:
Biological process: spermatogenesis
Cellular component: sperm annulus; motile cilium
Genetic constraint (gnomAD): Loss-of-function variants: 5 observed, 2.46 expected, observed/expected ratio (o/e) 2.03. That is too few expected variants to judge how well the gene tolerates losing a copy. Missense variants: 383 observed, 333.26 expected, observed/expected ratio (o/e) 1.15, 90% interval 1.06 to 1.25. Synonymous variants: 167 observed, 157.2 expected, observed/expected ratio (o/e) 1.06, 90% interval 0.94 to 1.21.
Homologues: Orthologues: chimpanzee CBY3 (98% identical), macaque CBY3 (90% identical), rat Cby3 (52% identical), dog CBY3 (46% identical), mouse Cby3 (39% identical). Paralogues in human: CBY2 (24% identical), CBY1 (22% identical), CCDC70 (8% identical).